SHC3 (SHC adaptor protein 3)
Description:
Signaling adapter that couples activated growth factor receptors to signaling pathway in neurons. Involved in the signal transduction pathways of neurotrophin-activated Trk receptors in cortical neurons.
Synonyms: N-Shc; NSHC; SHCC; RAI
Tractability: Antibody: its Gene Ontology location is reachable by antibodies, with medium confidence. PROTAC: its protein half-life has been measured.
Gene: Protein-coding gene on chromosome 9 (89,005,771 to 89,178,818, reverse strand). Ensembl gene ENSG00000148082.
Subcellular location (Human Protein Atlas): Nucleoplasm
Pathways (Reactome):
Signal Transduction: RAF/MAP kinase cascade; Signalling to RAS
Developmental Biology: RET signaling
Gene Ontology:
Molecular function: phosphotyrosine residue binding; protein binding; receptor tyrosine kinase binding
Biological process: cell surface receptor protein tyrosine kinase signaling pathway; central nervous system development; epidermal growth factor receptor signaling pathway; intracellular signal transduction
Cellular component: nucleoplasm; cytosol; plasma membrane
Genetic constraint (gnomAD): Loss-of-function variants: 14 observed, 51.99 expected, observed/expected ratio (o/e) 0.27, 90% interval 0.18 to 0.42. The upper end of that interval is the gene's LOEUF score, 0.42, which puts it in group 1 of 6, group 1 being the genes least tolerant of losing a copy. Missense variants: 583 observed, 647.64 expected, observed/expected ratio (o/e) 0.9, 90% interval 0.84 to 0.96. Synonymous variants: 256 observed, 259.15 expected, observed/expected ratio (o/e) 0.99, 90% interval 0.89 to 1.1.
Homologues: Orthologues: chimpanzee SHC3 (100% identical), macaque SHC3 (98% identical), pig SHC3 (92% identical), mouse Shc3 (91% identical), rat Shc3 (91% identical), dog SHC3 (89% identical), tropical clawed frog oma1 (66% identical), rabbit SHC3 (65% identical), guinea pig SHC3 (65% identical), zebrafish SHC3 (38% identical), Caenorhabditis elegans shc-1 (16% identical). Paralogues in human: SHC1 (47% identical), SHC4 (45% identical), CEP152 (17% identical).
Diseases named in the same sentence as SHC3 in open-access papers:
SHC3 is named in the same sentence as 30 diseases in open-access papers, as found by Europe PMC text mining. Sharing a sentence is not in itself a finding about the gene and the disease. The quoted sentences say what the papers report.
neuroblastoma (4 papers, 2007 to 2017). Neuroblastoma (NB) is the most common solid, extracranial childhood tumor. "Here, we demonstrated elevation of phosphopeptides from Ret and its Shc3 substrate in a MYCN-amplified neuroblastoma cell line, suggesting activation of this pathway in these cells." (PMID 24349301, 2013).
glioblastoma (3 papers, 2020 to 2022). The most malignant astrocytic tumor (WHO grade IV). "For example, SHC3 activates PI-3K/Akt in neurons and glioblastoma cells while in T lymphocytes it inhibits it." (PMID 32443613, 2020). "We also found that in glioblastoma cells either glucose deprivation or veliparib treatment decreased protein PARylation in the fractions enriched in SHC3 and glycosylated GLUT/SLC2A." (PMID 32443613, 2020). "Our results suggest that in glioblastoma cells, an early response to glucose starvation is increasing SHC3 intracellular levels." (PMID 32443613, 2020). "SHC3 is a bifunctional phosphotyrosine binding protein with two isoforms, p52SHC3 and p64SHC3, that were both increased in glioblastoma cells after glucose starvation." (PMID 32443613, 2020). "Also studies have reported that Shc3 is a new regulator of cancer stem cell migration, and Shc3 silencing in glioblastoma can reduce migration and invasion." (PMID 33723262, 2021). "Furthermore, cytosol extracted from glioblastoma cells inhibits PARP1 enzymatic activity in vitro while immunodepletion of SHC3 from the cytosol significantly relieves this inhibition." (PMID 32443613, 2020). "Here we show that in human glioblastoma cells maintained in exhausted medium, SHC adaptor protein 3 (SHC3) increases due to down-regulation of SHC3 protein degradation." (PMID 32443613, 2020). "We have recently shown that growing glioblastoma cells in monolayers at high cell density or in tridimensional spheroids leads to FAK activation and increases the intracellular levels of the two isoforms of SHC3: p52SHC3 and p64SHC3." (PMID 32443613, 2020).
hepatocellular carcinoma (3 papers, 2020 to 2021). A malignant tumor that arises from hepatocytes. "Prior studies have implicated these TRIP13 targets in the progression of various cancers, including COL6A3 and KLK7 in CRCs, SHC3 in hepatocellular carcinomas, and TREM2 in gastric cancers and renal cell carcinomas." (PMID 33037736, 2020). "COL6A3 and KLK7 in CRCs, SHC3 in hepatocellular carcinomas, and TREM2 in gastric cancers and renal cell carcinomas are associated with tumor growth." (PMID 33037736, 2020). "SHC3 regulates signal transduction, thereby stimulating hepatocellular carcinoma proliferation, migration, invasion, and epithelial-to-mesenchymal transition (EMT)." (PMID 32143735, 2020).
breast carcinoma (2 papers, 2018 to 2023). "Next, we attempt to investigate the potential mechanisms underlying Shc3‐induced chemoresistance and aggressive behavior in breast cancer." (PMID 36880347, 2023). "However, the molecular mechanism underlying the interplay between P‐gp and Shc3 in breast cancer is unknown." (PMID 36880347, 2023). "Then, we evaluated the effect of Shc3 upregulation on MDR1 activation in three breast cancer cell lines (MCF‐7/ADR, SK‐BR‐3 and MCF‐7)." (PMID 36880347, 2023). "This study found that multidrug‐resistant breast cancer cells exhibit pronounced upregulation of Shc3 expression and that Shc3 regulates the expression of the MDR1 gene, a crucial factor in drug resistance." (PMID 36880347, 2023). "Kaplan–Meier analysis also showed that patients with breast cancer who had high Shc3 levels had shorter overall survival (p = 0.0035)." (PMID 36880347, 2023). "Shc3 is also required for the drug resistance breast cancer cells by mediating nuclear translocation of ErbB2, thereby facilitating P‐gp expression by promoting ErbB2‐COX2‐MDR1 axis activity." (PMID 36880347, 2023). "In summary, we provide data indicating a pivotal role of Shc3 in the acquisition of chemoresistance and migration ability in breast cancer cells." (PMID 36880347, 2023). "According to these findings, Shc3 expression in breast cancer cells can impair chemosensitivity in vivo." (PMID 36880347, 2023). "In this study, we discovered a novel role for Src homolog and collagen homolog 3 (Shc3, also called Rai, ShcC, and N‐Shc) in regulating breast cancer drug resistance." (PMID 36880347, 2023). "We further found that Shc3 acts as a link mediating the binding between EphA2 and ErbB2 in breast cancer cells, resulting in increased activation of MAP kinase and AKT signaling pathways." (PMID 36880347, 2023). "Taken together, these results reveal that Shc3 induces chemoresistance and aggressive behavior in breast cancer cells." (PMID 36880347, 2023). "Here, we found that ectopic overexpression of Shc3 was detected specifically in drug‐resistant breast cancer cells, consequently reducing sensitivity to chemotherapy and promoting cell migration by mediating P‐gp expression." (PMID 36880347, 2023). "Our results show the crucial roles of Shc3 and ErbB2 in modulating P‐gp efficacy in breast cancer cells and suggest that Shc3 inhibition may enhance the sensitivity to chemotherapeutic drugs that target oncogene addiction pathways." (PMID 36880347, 2023). "We found that enhanced Shc3 expression was detected in MDR breast cancer cell lines." (PMID 36880347, 2023). "Hence, we hypothesized that Shc3 might act as a novel adaptor between EphA2 and ErbB2 in breast cancer cells." (PMID 36880347, 2023). "To further investigate the drug resistance potential of Shc3 in MCF‐7/ADR cells in vivo, we established a xenograft model of multidrug‐resistant breast cancer by subcutaneous inoculation of mice with MCF‐7/ADR‐Vector or MCF‐7/ADR‐Shc3 cells." (PMID 36880347, 2023). "Collectively, our findings suggested that the interaction of Shc3 with EphA2 and ErbB2 plays an important role in MDR and aggressive behavior of breast cancer." (PMID 36880347, 2023). "In this study, we demonstrated that Shc3 acts as a novel binding protein of EphA2 and ErbB2 linking that activated Akt and MAPK pathways to mediate drug resistance and aggressive behavior in breast cancer." (PMID 36880347, 2023). "Other downregulated genes, including breast cancer anti-estrogen resistance protein 1 (BCAR1, also known as p130Cas) and SHC adaptor proteins 3 and 4 (SHC3, SHC4), are key players in the regulation of cell migration by acting as scaffolds for tyrosine kinase-related signaling." (PMID 30086712, 2018). "Therefore, we hypothesized that Shc3 could modulate the function of this complex, thereby regulating MAPK and Akt pathway activation to promote drug resistance and aggressive behavior in breast cancer cells." (PMID 36880347, 2023).
alcoholism (1 paper, 2022). "Interestingly, the GO term “alcoholism” was enriched in genes associated with the “CGI-free intergenic UMR” category, including Shc3, Shc4, Araf, Fosb, Hdac11, Adcy5, Creb3l2, Gnai2, Grin2d, and Ppp1r1b." (PMID 35205351, 2022).
bone osteosarcoma (1 paper, 2020). A usually aggressive malignant bone-forming mesenchymal neoplasm arising from the bone. "Interestingly, in a proteome wide study of PARylated proteins present in human bone osteosarcoma-derived UOS2 cells that do not express SHC3, the closely related protein SHC1 was identified as PARP1 target." (PMID 32443613, 2020).
colorectal cancer (1 paper, 2020). A primary or metastatic malignant neoplasm that affects the colon or rectum. "Furthermore, it establishes role of TRIP13 in colorectal cancer metastasis and identifies COL6A3, TREM2, SHC3, and KLK7 as its downstream targets." (PMID 33037736, 2020).
glioma (1 paper, 2023). A benign or malignant brain and spinal cord tumor that arises from glial cells (astrocytes, oligodendrocytes, ependymal cells).
Obesity (1 paper, 2021). Accumulation of substantial excess body fat. "In the present study, the DEPs included Frs2 and Shc3, which represent novel candidate pharmaceutical targets for obesity based on their close links to pathways involved in obesity." (PMID 34840970, 2021).
sarcoma (1 paper, 2025). A usually aggressive malignant neoplasm of the soft tissue or bone.
substance dependence (1 paper, 2023). The psychological or physiological need to take a substance in order to experience its effects or to avoid the effects of its absence. "These included genes conferring heritable risk for nicotine and other substance dependence, such as GABBR2 encoding a GABAB receptor, and SHC3 involved in MAP kinase and neurotrophin signaling." (PMID 37699936, 2023).
tumor (9 papers, 2018 to 2024). "For example, previous studies have shown that SHC3 is functionally relevant to TRIP13-mediated tumor growth and metastasis." (PMID 35155682, 2022). "P-gp and β-catenin were increased in tumor tissues of mice injected with Shc3-overexpressing MHCC97L cells." (PMID 33723262, 2021). "Correspondingly, IHC staining of the tumor tissues for Shc3 confirmed the efficiency of Shc3 overexpression and revealed the correlation between Shc3 and the levels of P-gp and β-catenin in vivo." (PMID 33723262, 2021). "We observed a dramatically higher expression of Shc3 in HCC tumor than in the para-tumors (82.69%, 43 of 52); higher MDR1 transcript levels were observed in 80.76% (42 of 52) of HCC samples than its corresponding para-tumor tissues." (PMID 33723262, 2021). "All these results indicated that Shc3 promotes tumor stemness." (PMID 33723262, 2021). "Higher expression of Shc3 was detected in 46 of the 72 samples when expression of Shc3 was compared with that of the corresponding non-tumor liver tissues, and Shc3 protein expression was similar to P-gp protein expression in HCC samples (χ2 = 7.127, P = 0.007)." (PMID 33723262, 2021). "Moreover, recent reports have indicated that EMT induction in tumor cells not only contributes to increased metastasis, but also leads to MDR, and we presume that Shc3 is associated with drug sensitivity." (PMID 33723262, 2021). "After doxorubicin treatment, Shc3 overexpression group tumor volume reduced 34.50% compared with doxorubicin untreatment MCF‐7/ADR‐Shc3 group; control group tumor volume reduced 66.95% compared with doxorubicin untreatment MCF‐7/ADR‐Vector group." (PMID 36880347, 2023). "Thereafter, we examined Shc3 and P-gp protein expression in paraffin-embedded HCC tissue samples and adjacent para-tumor samples from 72 additional patients using IHC." (PMID 33723262, 2021). "The mRNA levels of Shc3 and MDR1 in HCC tumor tissues and adjacent para-tumor samples were compared." (PMID 33723262, 2021). "Additionally, RNA sequencing of CRC cells with TRIP13 knockdown identified COL6A3, TREM2, SHC3, and KLK7 as downstream targets that may have functional relevance in TRIP13‐mediated tumor growth and metastasis." (PMID 33037736, 2020).
cancer (8 papers, 2020 to 2025). A tumor composed of atypical neoplastic, often pleomorphic cells that invade other tissues. "SHC3 is ectopically overexpressed in various cancers and associated with their progression." (PMID 36419120, 2022). "We next sought to understand the mechanisms by which Shc3 promotes cancer cell stemness and drug resistance in HCC." (PMID 33723262, 2021). "Considering the importance of cancer stem cells in chemoresistance and cancer recurrence, we examined the influence of Shc3 on HCC stemness." (PMID 33723262, 2021). "Recently, several studies on Shc3 in malignant tumors have been conducted." (PMID 33723262, 2021). "In neuroblastoma cells, the interplay between Shc3 and HIF-1α may protect of cancer cells against hypoxia." (PMID 33723262, 2021).
psychiatric disorder (1 paper, 2024). A disorder characterized by behavioral and/or psychological abnormalities, often accompanied by physical symptoms. "We identified 7 genes (Cap2, Shc3, Lrrc7, Rims2, Cntnap2, Tcf20, and Trank1) associated with neurodevelopmental and psychiatric disorders that feature social impairments." (PMID 38263132, 2024).
SHC3 also shares sentences with these, for which no sentence is quoted: gastric cancer (2 papers); prostate carcinoma (2); astrocytomas (1); COVID-19 (1); epilepsy (1); experimental autoimmune encephalomyelitis (1); Hip dysplasia (1); leiomyoma (1); lymph node metastasis (1); multinodular goiter (1); neurological disorders (1); prolactinoma (1); renal cell carcinoma (1); Salmonella Infections (1); status epilepticus (1); thyroid carcinomas (1).